RNU6-904P (RNA, U6 small nuclear 904, pseudogene)
Gene: Small nuclear RNA gene on chromosome 2 (141,167,257 to 141,167,357, reverse strand). Ensembl gene ENSG00000252015.
Homologues: Orthologues: chimpanzee U6 (100% identical), pig U6 (74% identical), rat LOC120098438 (73% identical), dog RNU6-904P (67% identical). Paralogues in human: RNU6-211P (76% identical), RNU6-657P (76% identical), RNU6-1060P (75% identical), RNU6-116P (75% identical), RNU6-345P (75% identical), RNU6-406P (75% identical), RNU6-686P (75% identical), RNU6-1152P (74% identical), RNU6-1251P (74% identical), RNU6-154P (74% identical), RNU6-199P (74% identical), RNU6-470P (74% identical), and 1288 more.